RNASEH2A (ribonuclease H2 subunit A)
Description:
Catalytic subunit of RNase HII, an endonuclease that specifically degrades the RNA of RNA:DNA hybrids. Participates in DNA replication, possibly by mediating the removal of lagging-strand Okazaki fragment RNA primers during DNA replication. Mediates the excision of single ribonucleotides from DNA:RNA duplexes.
Synonyms: AGS4; RNASEHI; RNHIA; RNHL
Tractability: Small molecule: it has a high-quality binding pocket. PROTAC: ubiquitination databases record sites on it; its protein half-life has been measured.
Gene: Protein-coding gene on chromosome 19 (12,806,505 to 12,813,643, forward strand). Ensembl gene ENSG00000104889.
Subcellular location: Nucleus
Subcellular location (Human Protein Atlas): Nucleoplasm; Cytosol
Gene Ontology:
Molecular function: protein binding; RNA-DNA hybrid ribonuclease activity; RNA nuclease activity; nucleic acid binding; RNA binding
Biological process: mismatch repair; RNA catabolic process; DNA replication; ribonucleotide excision repair; RNA metabolic process
Cellular component: cytosol; nucleoplasm; ribonuclease H2 complex; nucleus
Genetic constraint (gnomAD): Loss-of-function variants: 30 observed, 34.97 expected, observed/expected ratio (o/e) 0.86, 90% interval 0.64 to 1.16. The upper end of that interval is the gene's LOEUF score, 1.16, which puts it in group 5 of 6, group 1 being the genes least tolerant of losing a copy. Missense variants: 409 observed, 402.76 expected, observed/expected ratio (o/e) 1.02, 90% interval 0.94 to 1.1. Synonymous variants: 147 observed, 165.9 expected, observed/expected ratio (o/e) 0.89, 90% interval 0.77 to 1.02.
Gene-disease validity (ClinGen):
ClinGen rates the evidence that RNASEH2A causes each of these diseases.
RNASEH2A-related type 1 interferonopathy (autosomal recessive): Definitive. Any type 1 interferonopathies in which the cause of the disease is a variation in the RNASEH2A gene.
Homologues: Orthologues: chimpanzee RNASEH2A (98% identical), macaque RNASEH2A (96% identical), mouse Rnaseh2a (87% identical), dog RNASEH2A (86% identical), rat Thsd8 (86% identical), guinea pig RNASEH2A (86% identical), pig RNASEH2A (80% identical), zebrafish rnaseh2a (63% identical), tropical clawed frog rnaseh2a (61% identical), Drosophila melanogaster CG13690 (48% identical), Caenorhabditis elegans rnh-2 (48% identical).
Diseases named in the same sentence as RNASEH2A in open-access papers:
RNASEH2A is named in the same sentence as 42 diseases in open-access papers, as found by Europe PMC text mining. Sharing a sentence is not in itself a finding about the gene and the disease. The quoted sentences say what the papers report.
Aicardi-Goutières syndrome (15 papers, 2010 to 2025). "The third CNV is located at 19p13.13 and overlaps with the gene RNASEH2A ribonuclease H2, subunit A (RNASEH2A) whose mutations may be responsible for the Aicardi-Goutieres syndrome (OMIM: 610333)." (PMID 20500880, 2010). "RNASEH2A (RNase H2 subunit A) was a protein encoding gene, and its RNASEH2A related diseases include Aicardi-Goutieres syndrome and Aicardi-Goutieres syndrome, associated with cancer progression and cell cycle." (PMID 35309134, 2022). "Idiopathic/familial perniosis, chilblain lupus and Aicardi–Goutières syndrome are associated with mutations in TREX1 and RNASEH2A." (PMID 32779733, 2021). "Aicardi-Goutieres syndrome (AGS) is an early-onset encephalopathy that can be caused by a gene mutation in one of 7 discovered genes so far (TREX1, RNASEH2B, RNASEH2C, RNASEH2A, SAMHD1, ADAR1, and IFIH1)." (PMID 32737687, 2020). "In the severe neuroinflammatory disorder Aicardi-Goutières syndrome, more than 50% of total AGS patients have biallelic mutations in one of the three genes encoding RNase H2: 5% for RNASEH2A, 36% for RNASEH2B, and 12% for RNASEH2C." (PMID 32069311, 2020). "In addition, Jafarpour described a de novo mutation in RNASEH2A, which is one of the genes, along with SAMHD1 (case 12) and RNASEH2B (sibling of case 13) that can cause Aicardi-Goutières Syndrome (AGS), a type 1 interferonopathy, autoinflammatory disorder." (PMID 40894167, 2025). "Certainly in the autoimmune vasculitis variants known as Aicardi-Goutières syndrome, where altered degradation of cytosolic DNA or RNA is caused by mutations in TREX1/SAMHD1/RNASEH2A/B/C/ADAR/IFIH1/PNPT1, the progressive immune activation leads to phenotypes of neuro-inflammation/-degeneration." (PMID 34345994, 2021). "The genetic dissection of a particular type I interferonopathy, Aicardi-Goutières syndrome, initially described as an early-onset progressive brain disease, identified mutations of the TREX1, RNASEH2A, RNASEH2B, RNASEH2C, SAMHD1, ADAR, and MDA5 genes as causal." (PMID 27190218, 2016). "Aicardi-Goutieres syndrome is classified as a monogenic interferon disease resulting from an aberrant mechanism involving intracellular nucleic acid sensing mediated by TREX1, RNASEH2A, RNASEH2B, RNASEH2C, SAMHD1, ADAR1 or IFIH1." (PMID 39286150, 2024).
prostate carcinoma (6 papers, 2014 to 2025). A carcinoma that arises from epithelial cells of the prostate gland. "Collectively, we propose that RNASEH2A overexpression is a hallmark of prostate cancer progression by maintaining genomic stability to prevent R-loop–mediated apoptosis induction." (PMID 36923313, 2022). "RNASEH2A was identified as a susceptibility gene for aggressive prostate cancer and, in another report, data from Oncomine revealed increased expression of RNASEH2A in a set of human cancers compared to normal tissue." (PMID 31125342, 2019). "It was previously reported that constitutive RNASEH2A overexpression protected LNCaP prostate cancer cells against CPT or etoposide and that RNase H2 depletion increased HU sensitivity in HeLa cells." (PMID 40640336, 2025). "RNASEH2A (ribonuclease H2, subunit A), known for its role in protecting the genomic integrity and progression of prostate cancer, had the most remarkable increase in the cultured Φ (39.42×) and Θ (49.10×) cells." (PMID 38790250, 2024). "We investigated the clinical implications of RNASEH2A expression in prostate cancer and elucidated the role of RNASEH2A in the progression of CRPC." (PMID 36923313, 2022). "Taken together, these observations indicate that high expression of RNASEH2A is an exacerbation factor for prostate cancer." (PMID 36923313, 2022). "First, we explored the role of RNASEH2A in maintaining genomic integrity in prostate cancer cells by affecting RNase H2 activity." (PMID 36923313, 2022). "In this study, we demonstrated that the overexpression of RNASEH2A is one of the mechanisms that accelerate castration resistance in prostate cancer." (PMID 36923313, 2022). "Taken together, these results indicate the important role of RNASEH2A in the aggressiveness of prostate cancer tumors." (PMID 36923313, 2022). "RNASEH2A immunostaining was detected in both the nuclei and cytoplasm of the prostate cancer tissues." (PMID 36923313, 2022). "Interestingly, we showed that RNASEH2A suppressed R-loop levels to prevent cell apoptosis induced by DNA damage in prostate cancer cells." (PMID 36923313, 2022). "Furthermore, dot plot analysis showed that R-loop accumulation in prostate cancer cells was promoted by RNASEH2A silencing, suggesting the effect of RNASEH2A expression on RNase H2 activation." (PMID 36923313, 2022). "RNASEH2A was demonstrated to be highly upregulated in aggressive prostate cancer to degrade R-loop accumulation and preserve genomic stability for tumor growth, suggesting that RNase H2 activity could be a promising therapeutic target." (PMID 36923313, 2022). "The IR of RNASEH2A was higher in CRPC tissues than localized prostate cancer tissues." (PMID 36923313, 2022). "Knockdown of RNASEH2A in prostate cancer cells led to increased nuclear γH2A immunostaining." (PMID 36923313, 2022). "Notably, high expression of RNASEH2A in prostate cancer tissues predicts poor prognosis in patients with prostate cancer." (PMID 36923313, 2022). "Recent work suggests that RNase H2 subunits and cellular activity, as well as RNase H2 localisation to HO-TRCs, might be responsive to RS produced by the chemotherapeutic agents CPT and HU, and RNASEH2A overexpression in prostate cancer cells can attenuate CPT-induced apoptosis." (PMID 41378389, 2025). "Thus, we focused on the role of RNASEH2A in advanced prostate cancer." (PMID 36923313, 2022). "Interestingly, the expression of RNASEH2A was found to be upregulated in CRPC, while that of RNASEH2B was downregulated in prostate cancer according to the publicly available database, as observed in a previous study." (PMID 36923313, 2022). "In the current study, we report that ribonuclease H2 subunit A (RNASEH2A), a conserved catalytic subunit of RNase H2, is one of the genes that are highly upregulated in CRPC tissues compared with benign prostate and prostate cancer tissues." (PMID 36923313, 2022).
breast carcinoma (5 papers, 2021 to 2025). "More recently, RNASEH2A overexpression was associated with cancer cell resistance to chemotherapy in vitro and with aggressiveness and poor outcomes in breast cancers of estrogen receptor (ER)-positive subtypes." (PMID 33805806, 2021). "Consistent with our results, knockdown of RNASEH2A was reported to decrease the activity of RNase H2 in breast cancer." (PMID 36923313, 2022). "Over expression of RNASEH2A is positively correlated with chemoresistance of breast cancer cells." (PMID 35449547, 2022). "RNASEH2A is a mediator of the removal of lagging-strand Okazaki fragment RNA primers, thus it can be integral in the proliferation of both triple-negative and endocrine-resistant breast cancers." (PMID 35401937, 2022). "RNASEH2A, a member of the RNase HII family, plays critical roles in the invasiveness and chemoresistance of breast cancer, proliferation and apoptosis in glioma, DNA damage response and cell viability of T cell leukemia." (PMID 40432923, 2025).
ovarian carcinoma (5 papers, 2020 to 2024). A malignant neoplasm originating from the surface ovarian epithelium. "Furthermore, we found a strong correlation between E2F1 and RNaseH2A expression and an inverse correlation between RNaseH2A expression and poor prognosis in patients with colorectal, cervical, or ovarian cancer via TCGA database analysis." (PMID 36577784, 2022). "Consistently, RNaseH2A knockdown also tended to increase SASP factor gene expression and invasion capacity in SK-OV-3 ovarian cancer cells." (PMID 36577784, 2022). "Furthermore, we confirmed that protein levels of ASF1B, CCNE1, CDC20, and RNASEH2A were significantly increased in ovarian cancer cells compared with non-transformed ovarian cells." (PMID 39199556, 2024).
cervical cancer (3 papers, 2021 to 2022). A primary or metastatic malignant neoplasm involving the cervix. "Similarly, we found that RNASEH2A is highly expressed in cervical cancer and participates in RNA catabolic process, which is expected to become a molecular diagnostic marker and therapeutic target of cervical cancer." (PMID 35449547, 2022). "Statistical analysis showed that the expression of RNASEH2A in cervical cancer was higher than that in adjacent tissues." (PMID 35449547, 2022). "Nonetheless, higher expression level of HENMT1, RBM38 and RNASEH2A showed a better overall survival of cervical cancer patients." (PMID 34863153, 2021). "Of interest, the induction of RNASEH2A by E2F1 has been also reported in human papillomavirus cervical cancers." (PMID 33805806, 2021). "This notion was also suggested by others showing that knocking out RNASEH2A in cervical cancer HeLa cells results in an increased sensitivity to ataxia telengiectasia and Rad3-related (ATR) inhibitors compared to knocking out RNASEH2B." (PMID 33805806, 2021). "In addition, increased levels of RNASEH2A in cancer compared to normal tissues and cells were also reported in cervical cancer, prostate cancer, colorectal carcinoma, and triple negative breast cancer." (PMID 33805806, 2021). "Finally, protein expression levels of RNASEH2A and HENMT1 in cervical cancer and adjacent tissues were verified by immunohistochemistry." (PMID 35449547, 2022).
glioma (3 papers, 2021 to 2025). A benign or malignant brain and spinal cord tumor that arises from glial cells (astrocytes, oligodendrocytes, ependymal cells). "RNASEH2A participates in the occurrence of human glioma by promoting glioma cell proliferation and inhibiting apoptosis." (PMID 35449547, 2022). "Their findings suggested a role of RNASEH2A upregulation in cell growth and apoptosis, contributing to glioma-genesis and cancer progression." (PMID 33805806, 2021).
colorectal cancer (2 papers, 2018 to 2022). A primary or metastatic malignant neoplasm that affects the colon or rectum. "It had been reported that RNASEH2A showed higher expression level in colorectal cancer, and this was validated in our research." (PMID 29651323, 2018). "Real-time PCR showed that MCM2, RNASEH2A, and TOP2A were upregulated in colorectal cancer compared with adjacent mucosa samples (MCM2, P < 0.001; RNASEH2A, P < 0.001; TOP2A, P = 0.001)." (PMID 29651323, 2018). "Our study confirmed that MCM2, RNASEH2A, and TOP2A were upregulated in colorectal cancer." (PMID 29651323, 2018). "Furthermore, RNaseH2A degradation using the auxin-inducible degron system induced the accumulation of nucleotide ligands and induction of certain tumourigenic SASP-like factors, promoting the metastatic properties of colorectal cancer cells." (PMID 36577784, 2022).
kidney cancer (2 papers, 2018 to 2021). Primary or metastatic malignant neoplasm involving the kidney. "As for CD151 knockdown experiments, the upregulation of RNASEH2A was observed in all kidney cancer cell lines and was associated with impaired tumor proliferation." (PMID 29843367, 2018). "High expression of RNaseH2A is involved in the progression of human gliomagenesis and kidney cancers." (PMID 33190424, 2021). "The combination of low CD151 expression and high RNASEH2A expression resulted in impaired proliferation in four kidney cancer cell lines, suggesting potential synthetic dosage lethality (SDL) interactions between the two genes." (PMID 29843367, 2018). "In search of an alternative pathway that promotes tumor proliferation, we performed gene correlation studies in five kidney cancer patient samples with high RNASEH2A expression, low CDK1 expression, and bad clinical outcomes (death)." (PMID 29843367, 2018). "Taken together, besides RNASEH2A upregulation, the CD151-related pathway might contribute to tumor growth in CDK1-low kidney cancers." (PMID 29843367, 2018).
Werner syndrome (2 papers, 2022 to 2023). "Similarly, ribonuclease H2 subunit A (RNaseH2A) was shown to be downregulated in Werner syndrome cells as well as selected cancer cells." (PMID 37130431, 2023). "In addition, RNaseH2A expression was significantly decreased in aged mouse tissues and cells from individuals with Werner syndrome." (PMID 36577784, 2022).
autoimmune disease (1 paper, 2017). A disorder resulting from loss of function or tissue destruction of an organ or multiple organs, arising from humoral or cellular immune responses of the individual to their own tissue constituents. "Autoimmune diseases like AGS are clearly linked to nucleic acid metabolism since mutations in TREX1, RNASEH2A-2C, SAMHD1, ADAR1, or IFIH1 predispose individuals to disease (12, 48, –, 51)." (PMID 28679751, 2017).
bladder urothelial carcinoma (1 paper, 2021). "Further analyses of RNASEH expression levels throughout different stages of lung squamous adenocarcinoma, breast invasive carcinoma, and bladder urothelial carcinoma again highlighted specific upregulation of RNASEH2A from normal tissues to early stages and more advanced stages of these cancers." (PMID 33805806, 2021).
Cerebral atrophy (1 paper, 2021). Atrophy (wasting, decrease in size of cells or tissue) affecting the cerebrum. "Aicardi-Goutières (AGS) is a rare immune dysregulated disease due to mutations in TREX1, RNASEH2A, RNASEH2B, RNASEH2C, SAMHD1, ADAR1 or IFIH1, characterized by encephalopathy, dystonia, basal ganglia calcifications, white matter abnormalities, and cerebral atrophy." (PMID 33482855, 2021).
Cirrhosis (1 paper, 2020). A chronic disorder of the liver in which liver tissue becomes scarred and is partially replaced by regenerative nodules and fibrotic tissue resulting in loss of liver function. "We finally selected three upregulated hub genes (KPNA2, TARBP1, and RNASEH2A) for which expression was systematically increased from normal liver to cirrhosis and HCC tissues based on the GSE89377 dataset." (PMID 32213663, 2020).
liver cancer (1 paper, 2025). An epithelial or non-epithelial malignant neoplasm that arises from the liver. "Similarly, the expression levels of LSM4 (p = 0.072) and RNASEH2A (p = 0.036) were also elevated in liver cancer organoids." (PMID 40432923, 2025).
microcephaly (1 paper, 2020). A congenital or acquired developmental disorder in which the circumference of the head is smaller than normal for the person's age and sex. "AGS caused by mutations in TREX1, RNASEH2A, and RNASEH2C usually presents early in the neonatal period as “pseudo-TORCH” manifestations with severe neurological dysfunction in the form of progressive microcephaly, spasticity, psychomotor retardation, and may lead to death." (PMID 32737687, 2020).
neuroblastoma (1 paper, 2020). Neuroblastoma (NB) is the most common solid, extracranial childhood tumor. "We found several highly significant RBPs including RPL22L1, RNASEH2A, PTRH2, MRPL11 and AFF2, which remain uncharacterised in neuroblastoma." (PMID 32707690, 2020).
ovarian tumors (1 paper, 2024). "Except for ATAD2, expression of other genes (ASF1B, CCNE1, CDC20, CDCA8, RECQL4, RNASEH2A, and SMC4) was upregulated in ovarian tumors compared to non-cancerous tissue." (PMID 39199556, 2024).
Pca (1 paper, 2023). "Among the six DDR-related genes whose expression was upregulated in CRPC tissues, we recently reported that RNASEH2A overexpression maintains genomic stability to prevent R-loop-mediated apoptosis induction during Pca progression." (PMID 37950047, 2023). "By combining both KEGG analysis and GO term analysis, seven genes (RNASEH2A, RFC2, RFC4, LIG1, POLD1, POLD2, and POLE4) were identified as new biomarker genes upregulated in CRPC compared to localized Pca and associated with DNA replication and DNA repair." (PMID 37950047, 2023). "We identified six DDR-related genes (Ribonuclease H2 Subunit A (RNASEH2A), replication factor C subunit 2 (RFC2), RFC4, DNA Ligase 1 (LIG1), DNA polymerase D1 (POLD1), and DNA polymerase E4 (POLE4)) that were upregulated in CRPC compared with Pca tissues." (PMID 37950047, 2023).
progeria (1 paper, 2022). "Because RNASEH2A expression decreases with age, we examined RNaseH2A expression in patients with progeria." (PMID 36577784, 2022).
tongue cancer (1 paper, 2021). A malignant neoplasm affecting the tongue.
viral infection (1 paper, 2020). "This category contained the nucleases RNASE7, RNASEH2A, RNASE10, and EXO1, as well as proteins regulating nucleases, like the OAS-protein family that are known to activate RNase L activity upon viral infection." (PMID 32545414, 2020).